ATM (ATM serine/threonine kinase)
Diseases named in the same sentence as ATM in open-access papers (continued):
Sharing a sentence is not in itself a finding about the gene and the disease.
lymphoid tumors (17 papers, 2003 to 2023). "In this regard, the previously studied A-T mouse model harboring a different targeted ATM allele exhibited a significantly earlier onset of lymphoid tumors and shorter mean survival compared to our ATM-deficient mouse model." (PMID 33608602, 2021). "Olaparib also had in vitro activity against ataxia telangiectasia mutated (ATM)-deficient lymphoid tumors and in vivo activity in mice xenografted with ATM-deficient mantle cell lymphoma tumor." (PMID 33233320, 2020). "For example, ablating the ATM DNA damage response gene was associated with a high incidence of lymphoid tumors in mice, and mice with a haploinsufficiency mutation in the BubR1 mitotic checkpoint gene were prone to carcinogen-induced tumors." (PMID 29383140, 2017). "Overall, the ATM knockout and the ATM knockin mouse models provide genetic support in vivo for a significant increase in the rate of lymphoid tumor development associated with ATM deficiency." (PMID 24681585, 2014). "Also, ATM-deficient lymphoid tumor cells have shown vulnerability to olaparib in vitro and in vivo." (PMID 27447864, 2017). "Considering lymphoid tumor cells, PARP inhibition was shown to be cytotoxic for ATM-deficient cells, in vivo and in vitro." (PMID 29903986, 2018). "Nevertheless, the presence of a lymphoid tumour in both affected individuals does raise the interesting possibility that PALB2 may represent a novel tumour suppressor of lymphoid malignancies in a manner similar to ATM and NBN." (PMID 26990772, 2016).
T-cell lymphomas (17 papers, 2014 to 2023). "Cbl-b deficient mice can efficiently reject transplanted tumor xenografts, ultraviolet-light-induced skin tumors, and spontaneously generated T-cell lymphomas in an ataxia telangiectasia mutated (ATM) deficient background." (PMID 31756921, 2019). "Similarly, in mice, both ATM deletion and activating mutations of β−catenin have been shown to induce a DP-stage maturation block, and T-cell lymphomas." (PMID 28881594, 2017). "Among these cooperating changes is loss of ATM, which induces rapid T-cell lymphoma development." (PMID 26984279, 2016). "In the present study, we report encouraging preclinical data describing the benefits of ATM inhibition in promoting CHOEP-induced cell death in preclinical models of T-cell lymphoma using two different chemical compounds—AZD0156 and KU-55933." (PMID 35409194, 2022). "In line with this, our data showed that deletion of Gadd45a increased the incidence of T-cell lymphoma in ATM−/− mice." (PMID 24474198, 2014). "The delayed death due to T-cell lymphoma development in Atm−/−; Erk5−/− mice suggests that pharmacological targeting of ERK5 has therapeutic potential for T-cell lymphoma patients carrying inactivating ATM mutations." (PMID 30901834, 2019). "Indeed, in the absence of ERK5, the development of T-cell lymphoma in Atm−/− mice is reduced, revealing a functional interaction between ATM and ERK5 (see also the section “Genome Instability”)." (PMID 30901834, 2019). "Furthermore, when crossing ataxia telangiectasia mutated (ATM) deficient mice onto a cblb-deficient background, 50% of ATM−/−cblb+/+ mice died within 6 months of age of spontaneous T cell lymphomas while no death was observed among ATM−/−cblb−/− double knockout mice." (PMID 25815272, 2015).
acute lymphoblastic leukemia (16 papers, 2011 to 2026). Leukemia with an acute onset, characterized by the presence of lymphoblasts in the bone marrow and the peripheral blood. "A high frequency of chromothripsis has also been detected in acute lymphoblastic leukemia with mutations in Ataxia-telangiectasia mutated (ATM), a key signaling kinase of HR." (PMID 36761982, 2023). "The ATM/ATR pathway has been shown to be activated by CX-5461 in acute lymphoblastic leukemia cells." (PMID 33963218, 2021). "Mohammad A speculated that ATM deficiency might increase the sensitivity of leukemic blasts to the chemotherapy used during induction and after disease remission in patients with adult ALL (Acute Lymphoblastic Leukemia)." (PMID 21496344, 2011). "As with AML, ATM signaling to the NF-kB pathway promotes tumor survival in acute lymphoblastic leukemia (ALL)." (PMID 38347838, 2024). "Additionally, accumulating evidence indicates that ATM drives the BM-mediated resistance to chemotherapy in other hematological malignancies, such as multiple myeloma and acute lymphoblastic leukemia via upregulation of cytokines such as IL-6 or CCL3, CCL4, and GDF15." (PMID 36259537, 2022). "The ATM (ATM Serine/Threonine Kinase) inhibitor (AZD0156) and staurosporine inhibit the phosphorylation of TET1 (tet methylcysteine dioxygenase 1), causing instability of the TET1 protein and demonstrating a synergistic killing effect on B-ALL (B cell acute lymphoblastic leukemia) cells." (PMID 38474445, 2024). "In acute leukemia, Haidar and colleagues reported a high frequency of ATM deletions (10 out of 36; 28%), including 7 (19.4%) cases with loss of heterozygosity (LOH) and 3 (8.4%) cases with homozygous deletions in adult acute lymphoblastic leukemia (ALL) patients." (PMID 28356161, 2017).
myocardial infarction (16 papers, 2013 to 2025). Gross necrosis of the myocardium, as a result of interruption of the blood supply to the area, as in coronary thrombosis. "The increase of SLC2A3, EPAS1 and HMOX1 were risk factors for myocardial infarction, while ATM and FANCD2 were protective factors." (PMID 38253721, 2024). "ATM is a vital signal‐transducing kinase for mediating certain forms of DNA damage, and deficiency of ATM delays the inflammatory response such as the accumulation of neutrophils and macrophages post myocardial infarction." (PMID 38668740, 2024). "In contrast, reduced expression of numerous DNA repair genes, including ERCC1, XPA, and ATM, are associated with stable angina and myocardial infarction." (PMID 36734200, 2023). "While these studies hold promise of ATM inhibition in myocardial infarction, several investigations demonstrated that ATM deficiency aggravated postmyocardial infarction cardiac dysfunction and remodeling via disturbed autophagy and angiogenesis." (PMID 36156462, 2023). "ATM deficiency results in autophagic impairment in myocardial infarction." (PMID 39119608, 2024). "Interestingly, mice with ATM haplo-deficiency had decreased vascular endothelial growth factor production and impaired angiogenesis in response to myocardial infarction, leading to accelerated heart failure." (PMID 31788461, 2019). "SLC2A3, EPAS1, HMOX1, ATM and FANCD2 genes all had good diagnostic value for myocardial infarction (P < 0.05)." (PMID 38253721, 2024). "The increase of SLC2A3, EPAS1 and HMOX1 are risk factors for myocardial infarction, while ATM and FANCD2 are protective factors.Decision tree analysis showed that SLC2A3, HMOX1, ATM, FANCD2 gene had higher net yield in diagnosing myocardial infarction." (PMID 38253721, 2024). "Although ATM inhibition has shown promising cardioprotective effects in heart failure, several studies have reported aberrant ATM activation in myocardial infarction." (PMID 36156462, 2023). "Haplodeficient ATM± mice also have worse cardiac remodeling and an impaired ventricular function post-myocardial infarction compared to their wild-type littermate, suggesting that ATM depletion facilitates the development of heart failure." (PMID 31921839, 2019). "This review summarizes the role of ATM in the heart, specifically in cardiac remodeling following β-adrenergic receptor stimulation and myocardial infarction." (PMID 29152614, 2017). "The results presented here suggest that ATM plays a multifaceted role in remodeling pathways following myocardial infarction." (PMID 24358288, 2013). "ROC curves of 5 different genes related to ferroptosis associated with myocardial infarction showed that SLC2A3, EPAS1, HMOX1, ATM and FANCD2 genes had good diagnostic value for myocardial infarction, and the elevation of SLC2A3, EPAS1 and HMOX1 was a risk factor for myocardial infarction." (PMID 38253721, 2024). "ATM is vital for myocyte apoptosis and cardiac remodeling following myocardial infarction." (PMID 39119608, 2024). "ROC curves of 5 differentially ferroptosis-related genes associated with myocardial infarction showed that SLC2A3, EPAS1, HMOX1, ATM and FANCD2 genes had good diagnostic value for myocardial infarction, and the area under the curve had statistical significance (P < 0.05)." (PMID 38253721, 2024). "In ATM heterozygous knockout mice, cardiac remodeling was attenuated after myocardial infarction." (PMID 36156462, 2023). "Furthermore, ATM was shown to trigger cardiac inflammation during myocardial infarction." (PMID 36156462, 2023).
myocardial infarction (continued). "Interestingly, APAF1 and IRAK3 expression correlated negatively with NK cell abundance in both acute myocardial infarction and ischemic stroke, whereas ATM, CAPN1, IL1B, IL1R1, PRKACA, PRKACB, and TNFRSF1A correlated negatively with NK cell abundance in acute myocardial infarction." (PMID 35432334, 2022). "Here we investigated the role of ATM in cardiac remodeling using myocardial infarction (MI) as a model." (PMID 24358288, 2013). "Using inhibitors of ATM, such as KU60019, ultimately restored levels of LARP7, SIRT1 and mitochondrial biogenesis preventing adverse remodeling effects of myocardial infarction (MI)." (PMID 40264508, 2025). "According to the method of systematic random sampling, the sample size was divided into test set and verification set, and the decision tree model of SLC2A3, EPAS1, HMOX1, ATM and FANCD2 genes on myocardial infarction was established." (PMID 38253721, 2024). "The results showed that SLC2A3, HMOX1, ATM and FANCD2 genes had higher net yield in the diagnosis of myocardial infarction." (PMID 38253721, 2024). "Myocardial infarction (MI) also increases ATM expression, as evidenced by increased ATM protein levels in the non-infarct and infarct regions of ATM wildtype (WT) and heterozygous knockout (hKO) hearts 1 and 3 days post-MI34." (PMID 29152614, 2017).
nasopharyngeal carcinoma (16 papers, 2011 to 2025). A carcinoma arising from the nasopharyngeal epithelium. "ATM overexpression has been correlated with poor response to radiotherapy and worse overall survival in rectal cancer and advanced nasopharyngeal carcinoma patients." (PMID 29845714, 2018). "In 2011, researchers found that in nasopharyngeal carcinomas with ATM deficiency, LINE-1 retrotransposition increased, and ORF2 copy number increased in AT neurons, thus verifying the correlation between LINE-1 retrotransposition and ATM deficiency." (PMID 32850797, 2020). "ZEB1, a transcription factor stabilized by ATM-mediated phosphorylation, suppresses the expression of miR-205-5p in nasopharyngeal carcinoma (NPC)." (PMID 41425255, 2025). "In nasopharyngeal carcinoma, metformin also sensitized cells to radiation through DNA repair pathway modulation, upregulation of p-ATM and p-ATR and downregulation of ATM, ATR, p95/NBS1, Rad50, DNA-PK, Ku70 and Ku80." (PMID 35327549, 2022). "In patients with nasopharyngeal cancer (NPC) receiving concurrent chemoradiotherapy, high ATM protein expression by quantitative fluorescent immunohistochemistry was associated with poor OS [hazard ratio (HR), 2.83; 95% CI, 1.01–7.94; p = .049]." (PMID 33224881, 2020). "In addition, biopsies of patients with EBV-positive nasopharyngeal carcinoma (NPC) revealed downregulation of ATM protein levels." (PMID 30662441, 2018).
B-cell lymphoma (15 papers, 2009 to 2022). "In individuals with B-cell lymphoma, the presence of a mutation in ATM is associated with a worse prognosis." (PMID 36514795, 2022). "Inactivating somatic ATM mutations are associated with T- and B-cell lymphoma; dysregulated V(D)J recombination results in translocations in ATM-deficient lymphocytes, potentially promoting tumorigenesis." (PMID 34970273, 2021). "As ATM is rightly considered as a tumor suppressor, ATM deficiency or deleterious alterations are commonly seen in solid tumors and B‐cell lymphoma." (PMID 34977872, 2021). "DNA-PKcs inhibition has been effective as a monotherapy in ATM-deficient B cell lymphomas in cell lines and pre-clinical models." (PMID 32015826, 2020). "ATM gene mutation were found in ocular adnexal marginal zone B-cell lymphomas and uveal melanoma." (PMID 34615949, 2021). "We therefore examined the therapeutic efficacy of combining inhibition of ATM/ATR signaling with CX-5461 in MYC driven B-cell lymphomas (Eμ-Myc)." (PMID 27391441, 2016). "FISH analysis from B-cell lymphoma panel showed bi-allelic amplification of ATM gene." (PMID 33541390, 2021). "Alternatively, B-cell lymphoma also developed when crossing the Emu-CCND1 mouse with transgenic mice that had other genetic aberrations observed in MCL, such as BIM-deficient or ATM-deficient mice." (PMID 27713153, 2016). "Furthermore, tumours bearing high levels of oncogene-induced DNA damage response (DDR), such as MYC driven murine lymphoma (Eμ-Myc) and human B-cell lymphomas, are sensitive to therapeutic targeting of DNA-dependent Protein Kinase (DNA-PK) and ATM/ ATR." (PMID 27391441, 2016). "In line with previous findings, we found that NL101 induces DNA damage in B cell lymphoma as ATR, ATM, CHK1 and CHK2 phosphorylation increase." (PMID 33537096, 2021).
myeloma (15 papers, 2011 to 2025). "Inhibiting DDR components, like PARP, ATR, WEE1, CHK1/2, ATM, and DNA-PKs, is under evaluation in early-phase studies for multiple myeloma and other hematological malignancies showing promising preliminary signals of activity." (PMID 41155462, 2025). "ATM inhibition through KU-55933 has been shown to have limited efficacy against multiple myeloma (MM) cells lines either alone or in combination with doxorubicin." (PMID 38347838, 2024). "LncRNA NEAT1 was over-expressed in multiple myeloma cells exposed in nutrient-deprived environment and provoked higher aggression by inducing two fundamental kinases (ATM and DNA-PKcs) and their targets (pRPA32 and pCHK2)." (PMID 36541918, 2022). "Several chemotherapeutic agents such as Adr, melphalan, and bortezomib were shown to induce CD155 expression on multiple myeloma cells, which was blocked by treatment with pharmacologic inhibitors of ATM/ATR-related kinases." (PMID 30039180, 2018). "ATM and ATR alterations (mutations and deletions) occur in a small subset of myeloma patients, respectively 4.3% and 1.5% of newly diagnosed patients." (PMID 29163849, 2017). "Moreover, nitric oxide donors were also found to stimulate CD155 expression on multiple myeloma cells through activation of ATM/ATR-related kinases." (PMID 30039180, 2018). "At the time point when myeloma achieved complete remission, while AML persisted, bulk sequencing still showed persistence of ATM (c.1262C>A)." (PMID 37852254, 2023). "Myeloma (MM1s), pancreas (ASPC-1) and colon (HCT 116) cancer cells were treated for 2 h with DNA damage response inhibitors (i.e. ATM inhibitor (KU-55933), DNA-dependent protein kinase catalytic subunit inhibitor (DNA-PK inhibitor II), and an alternative join repair inhibitor (PARP, NU1025)]." (PMID 38783375, 2024). "In other work, human multiple myeloma (MM) cells were treated with MEDI2228, a ligand of the B-cell maturation antigens that induces ATM/ATR-Chk1/2 pathway activation, in combination with different inhibitors of the principal kinases of the DDR (ATM, ATR, and WEE1)." (PMID 37655260, 2023). "One study showed ATM-dependent DDR to induce IL-6 secretion by BM stromal cells and subsequent myeloma cell chemoresistance; probing for the specific DDR cascade may reveal targetable mechanisms for future HM therapies." (PMID 34505878, 2021).